EGFR (epidermal growth factor receptor)
Diseases named in the same sentence as EGFR in open-access papers (continued):
Sharing a sentence is not in itself a finding about the gene and the disease.
cancer (continued). "This leaves a substantial portion of unresponsive cancers, making it clinically important to prospectively identify predictors of response and resistance to EGFR TKIs." (PMID 36647832, 2023). "The role of c-Cbl as a negative regulator of EGFR signaling has been well established using cancer cells or cell lines engineered to express exogenous EGFRs." (PMID 37830613, 2023). "The use of EGFR TKIs can also induce MET receptor amplification, which bypasses the EGFR pathway, causing signaling downstream to promote cancer cell proliferation and resistance to standard of care treatments." (PMID 36979929, 2023). "Cluster 1 was an epidermal growth factor receptor with the keywords cisplatin, chemoresistance, Akt, NF-kb, 5-fluorouracil, cancer stem cells, cetuximab, monoclonal antibody, and radiation." (PMID 38025895, 2023). "EGF secreted by TAMs activates the EGFR/extracellular signal-regulated kinase 1/2 signal pathway in some types of cancer cells, which results in the promotion of EMT." (PMID 38033495, 2023). "In cultures incubated with 1MAbs, the anti-EGFR antibody induced the highest activation of NK cells: from 12 to 20% for 1Cetu and from 15% to 24% for 1Matu, in function of the pancreatic target cancer cell line." (PMID 37153618, 2023). "The epidermal growth factor receptor, coded by the EGFR gene, triggers a signaling pathway that promotes cell growth and proliferation of cancer cells." (PMID 37834191, 2023). "Previous studies stated that the activation of KRas correlated with higher levels of expression of EGFR/MAPK in a plethora of human cancers." (PMID 37760426, 2023). "EGFR is a critical modulator and a target for developing novel therapeutic strategies in various cancers." (PMID 37601068, 2023). "This is a traditional area of research for developing anticancer drugs and many EGFR inhibitors have been used to treat human cancers." (PMID 36043746, 2023). "Currently there are two distinct groups of therapeutic agentsemployedfor targeting EGFR in cancer treatment." (PMID 37902816, 2023). "We also found that a high proportion of TNBC tumors express the immunohistochemical markers, i.e. CK5/6, CK14, CK17 or EGFR of basal-like cancers." (PMID 37599285, 2023). "The finding of correlation between predicted-not-to-benefit group and high-grade subtypes is consistent with a recent observation of prevalence of high-grade subtypes in patients with cancers resistant to EGFR TKI." (PMID 36647832, 2023). "We also observed a significant difference between the cancer-cell lines regarding the effects of the two EGFR inhibitors." (PMID 36769112, 2023). "In the case of the EGF, a self-antibody response against this molecule would diminish the serum availability of EGF, thus reducing EGFR activation and, in consequence, cancer-cell proliferation." (PMID 37241784, 2023). "While links between EGFR alteration and thrombosis have been documented in other cancers, the role of EGFR in GBM VTE has yet to be described thoroughly." (PMID 37232831, 2023). "Polythiophene modification of SPCE was carried out for tracking the immunocoplexes made of cancer biomarker epidermal growth factor receptor (EGFR) antigen and Nbs labeled-Fe3O4/N-trimethyl chitosan/AuNPs formed initially “in Eppendorf tube”." (PMID 37630022, 2023). "NmAb efficiently suppresses the proliferation of EGFR+ cancer cells by blocking the EGFR signaling cascade." (PMID 37623652, 2023). "The epidermal growth factor receptor (EGFR) plays a critical role in the tumorigenesis of various forms of cancer." (PMID 37111291, 2023).
cancer (continued). "EGFR targeted TKIs disrupt the immune suppressive TME by several mechanism including blocking cancer cell migration and nutrient delivery through targeting of endothelial cells and suppressing pericyte coverage." (PMID 37114134, 2023). "In vitro experiments confirmed the OMVs' proficiency in adhering to EGFR-overexpressed cancer cells." (PMID 37775519, 2023). "The epidermal growth factor receptor (EGFR) plays a crucial role as a therapeutic target in various cancer types." (PMID 37775519, 2023). "PROTAC is a revolutionary technology to overcome the resistance of EGFR inhibitors for effective cancer therapy." (PMID 37261210, 2023). "Epidermal growth factor receptor (EGFR) is a cancer marker in various carcinomas, including breast, head, neck, oesophagal, gastric, pancreatic, colorectal, prostate, bladder, renal, ovarian, and ovarian Non-Small Cell Lung Cancer (NSCLC)." (PMID 37445686, 2023). "EGFR inhibition has promising effects on both diseases, including inhibiting cancer cell migration and AD pathology (e.g., Aβ, neuroinflammation, and cognitive function)." (PMID 37601068, 2023). "Considering the epithelial origin of most cancers, EGFR expression deserves to be considered in the cancer treatment processes." (PMID 39144672, 2023). "Several recent studies have highlighted epidermal growth factor receptor (EGFR) inhibitors approved for use as anti-cancer drugs as potential candidates for repurposing as AD therapeutics." (PMID 37601068, 2023). "Nimotuzumab is an anti-EGFR IgG that is used as a therapeutic for EGFR positive cancers in a number of jurisdictions." (PMID 37419997, 2023). "EGFR inhibitors can potentially dock this protein, and these inhibitors can be used in the treatment of certain types of cancers related to overexpression of the EGFR gene." (PMID 36768973, 2023). "FDA-approved quinazolines constitute a promising group of drugs against different types of tumors in cancer and mechanistically inhibit the protein kinase of the epidermal growth factor receptor (EGFR), inactivating the anti-apoptotic pathway." (PMID 38005871, 2023). "Recent studies have demonstrated that epiregulin (EREG) is upregulated in various cancer types, which contributes to cancer progression by triggering the EGFR signaling pathway." (PMID 37020674, 2023). "In this phase I trial (NCT0199998), Dasatinib revealed high tolerance in cancer patients who progressed after EGFR inhibitors and feasibility in advanced NSCLC at biologically active dosages in conjunction with afatinib." (PMID 36902280, 2023). "Combining chemotherapy with the targeted therapy through EGFR-targeted by the small molecule TKIs is emerging as a very important therapeutic model in the cancer treatment scenarios to achieve a longer life expectancy for patients." (PMID 37128337, 2023). "While gain‐of‐function mutations in the ECD of RTKs (such as EGFR) have been reported, gain of function mutations in the RTK TKD are more prevalent in adult cancers." (PMID 37587872, 2023). "Modified VLPs delivered DOX to EGFR-expressing cancer tissues and exhibited a GSH-dependent drug release." (PMID 37020877, 2023). "The link between the altered EGFR gene and cancer has led to scientists developing targeted therapeutics against EGFR, which is easily accessible due to its vantage location on the cell surface." (PMID 38090376, 2023). "Recent studies have been indicated that EGFR signaling is dysregulated in various cancer types that acquire cisplatin resistance." (PMID 37165076, 2023). "Oridonin, a bioactive diterpenoid component, has been shown to suppress cancer cell proliferation via blocking the EGFR signaling pathway.." (PMID 36768973, 2023). "Epidermal growth factor receptor (EGFR) has become a promising target because it is overexpressed in TNBC cancer cells." (PMID 37691919, 2023).
cancer (continued). "PI4K2A maintains cancer cell survival and promotes tumorigenesis by enhancing EGFR protein stability and by facilitating trafficking of misfolded proteins to the lysosome." (PMID 36757799, 2023). "These OMVs were meticulously designed to selectively target cancer cells exhibiting an overexpression of epidermal growth factor receptor (EGFR)." (PMID 37775519, 2023). "Immunofluorescence analysis also revealed that there was a strong colocalization of JMJD5, HUWE1, and EGFR in cancer cells." (PMID 37813845, 2023). "This is often due to the over-expression of certain genes, such as EGFR, which can promote the survival and proliferation of cancer cells." (PMID 37803333, 2023). "Multiple microRNAs have been reported to modulate the expression of EGFR and its downstream signaling pathways in different cancers." (PMID 37114127, 2023). "Combined multi-omics and biochemical analyses indicate an elevated PI3K/AKT/p65 driven cell survival and cytokine production in rCAFs, while rCAF-secreted TGFα promotes cancer cell chemoresistance by activating EGFR/Src/STAT3 survival signaling axis." (PMID 37821657, 2023). "Cetuximab is a chimeric immunoglobulin G1 (IgG1) which targets EGFR, a member of receptor tyrosine kinases (TK) highly expressed in several types of cancers, including breast, lung, colorectal and head and neck cancers." (PMID 38077389, 2023). "Stronger effects have been found for sE-cad as compared to EGF, the classical ligand of EGFR, in increasing cancer cell proliferation and metastasis." (PMID 37760996, 2023). "EGFR is aberrantly glycosylated in cancer cells due to alterations in the expression and activity of various glycosyltransferases." (PMID 37660914, 2023). "To validate the RNA-seq analysis, we selected seven representative genes on the basis of their relevance for HGSOC (PAX8, EGFR) and other cancers (GATA6, RBM47, KHDRBS3), or for their involvement in the DDR pathway (ATRIP, POLH)." (PMID 37202753, 2023). "Because EGFR inhibitors are used in clinics for the treatment of several cancers, in this work, we characterized the role of EGFR on cardiomyocyte cohesion and the efficacy of erlotinib to modulate adhesion." (PMID 36795511, 2023). "We aimed to delineate the molecular changes occurring in EGFR mutant cancers that become TKI-resistant and subsequently transform from NSCLC to SCLC." (PMID 38188289, 2023). "Researchers have shown that they can identify and image cancer cells by conjugating anti‐EGFR to the surface of gold nanoparticles." (PMID 36840363, 2023). "At the molecular basis, HNSC is widely accepted to be one of the cancer types showing aberrant upregulated oncogenic receptor tyrosine kinase (e.g., Epidermal Growth Factor receptor, EGFR) activity." (PMID 38068962, 2023). "Studies have shown that inhibition of the kinase activity of cellular mesenchymal epithelial transition factor (c-Met) can restore the sensitivity of EGFR T790M mutant cancer cells to EGFR TK inhibitors, thereby overcoming the problem of drug resistance." (PMID 37108294, 2023). "EGFR is a receptor that is upregulated in many cancers, but the mechanisms that control EGFR function are incompletely understood." (PMID 37160944, 2023). "This gene encodes for the epidermal growth factor-like protein-7, which is known to facilitate tumorigenesis and angiogenesis through main cancer drivers from EGFR signaling to integrins, Notch receptor, or lysyl oxidase family members [reviewed in 60]." (PMID 37853459, 2023). "Analysis of human tissue data revealed that NUAK1 expression positively correlates with EGFR expression and Akt Ser-473 phosphorylation in several human cancers." (PMID 38135881, 2023). "Some of the most-commonly studied cancer biomarkers such as the epidermal growth factor receptors EGFR and HER2 or folate receptor were already thoroughly described in other reviews in regard to MIPs." (PMID 37376096, 2023).
cancer (continued). "The kinase-independent (KID) functions of EGFR promote cancer cell survival by supporting the import of nutrients, promoting autophagy, and inhibiting apoptosis." (PMID 37174055, 2023). "HBEGF (heparin-binding EGF-like growth factor) secreted by particulate matter-treated macrophages activated EGFR in cancer cells." (PMID 37830596, 2023). "The identification of the quinazoline core as a valuable scaffold for EGFR inhibition led to the development of several TKIs with tremendous clinical utility in various types of cancer (especially NSCLC)." (PMID 37111291, 2023). "ADCC phenomenon is triggered by cetuximab, an anti EGFR antibody, which is widely used in cancer immunotherapy, including also locally advanced or recurrent/metastatic HNSCC treated with platinum-based chemotherapy plus cetuximab or panitumumab." (PMID 36980527, 2023). "This led to the identification of MCLA-158, a bispecific antibody that binds the LGR5 marker and the EGFR on cancer stem cells, inducing a robust blocking of growth in organoids." (PMID 37189676, 2023). "As per this principle, it is possible that when treated with HER3 antibodies and inhibitors, cancer cells activate EGFR/HER2 or other alternative survival pathways to continue proliferation in a HER3-independent manner." (PMID 37163206, 2023). "All 60 cancer cell lines exhibited a synergistic response to combining daunorubicin and EGFR inhibitors." (PMID 37629110, 2023). "Although TKIs, represented by third‐generation EGFR‐TKIs, have achieved remarkable success in the field of cancer treatment, clinical results show that there are still inevitable toxic side effects in the gastrointestinal tract, skin and other organs." (PMID 37143582, 2023). "A problem with targeted therapies developed for cancer treatment, such as the EGFR inhibitors erlotinib, gefitinib, and lapatinib, is that they all can cause acneiform rash and diarrhea when given daily." (PMID 37169023, 2023). "Transcriptomic analyses indicated that cancer cells resistant to killing by EGFR CAR-T cells are characterized by enhanced expression of a set of immunosuppressive genes." (PMID 37189725, 2023). "In this regard, epidermal growth factor receptor (EGFR) overexpression/mutation is a frequent, cancer-specific event in TC: in an Egyptian population (N = 60) with TC, over 50% of patients harbored EGFR mutations (deletion ex 19)." (PMID 37173925, 2023). "When EGFR was activated, proliferation, differentiation, transformation, angiogenesis, migration, and survival of cancer cells were induced." (PMID 36770659, 2023). "Src is known as the activator of EGFR downstream signaling in cancer cells as a signaling transporter inducing phosphorylation of EGFR and causes the activation of the signal-regulating kinases, such as RAS and ERK." (PMID 37686097, 2023). "While there are US Food and Drug Administration (FDA) approved tests for EGFR mutations (cobas EGFR Mutation Test v2), NGS allows the ability to analyze multiple genes at the same time or the entire cancer genome." (PMID 36900386, 2023). "The abnormal expression and mutagenesis of EGFR drives both the development and progression of a multitude of human cancers." (PMID 37333807, 2023). "By summarizing the physiological functions of EGFR in cancer and AD, this review emphasizes the significance of EGFR as an important molecular target for these diseases." (PMID 37601068, 2023). "Whereas sapitinib has an enhanced pharmacologic profile due in part to equipotent inhibition of EGFR, erbB2, and erbB3, showing potent antitumor activity in preclinical cancer models." (PMID 36982163, 2023). "In contrast, this overexpression allowed researchers to utilize the EGFR’s inhibition as an essential strategy in cancer treatment." (PMID 36893122, 2023). "Our data suggests targeting the retrograde trafficking of EGFR is a novel mechanism to target EGFR-driven cancers through the competitive inhibition of binding between the EGFR kinase and the SNX1 BAR domain." (PMID 36253541, 2023).
cancer (continued). "This contributes to the increased CAF population in chemoresistant patient-derived tumors compared to chemosensitive patient-derived tumors and promotes cancer cell chemoresistance through TGFα-EGFR paracrine signaling." (PMID 37821657, 2023). "Gefitinib in combination with DNA topoisomerase I inhibitor CPT-11 exerts a powerful anti-cancer effect via the activation of apoptosis and the inhibition of EGFR phosphorylation in vitro and in vivo." (PMID 36768961, 2023). "High level of oxidative DNA damage was demonstrated in cancer thyroid tissue and proposed to be involved in disease progression through modulation of EGFR and its downstream signaling." (PMID 37114127, 2023). "In many cancers, EGFR plays a major role in the development of these carcinomas and is often regarded as an important biomarker for a negative prognosis." (PMID 37370810, 2023). "Many studies have shown that EGFR is overexpressed in a variety of cancers, including lung, glioma, esophageal, colorectal and head and neck cancer." (PMID 37085908, 2023). "As important membrane surface receptors, other membrane proteins are likely to play important roles in promoting EGFR‐related cancer." (PMID 38107059, 2023). "Another recent study showed that an alternative mechanism to EGFR-dependent macropinocytosis takes place in the PDAC stroma, through AMPK activation by the PDAC stromal cancer-associated fibroblasts (CAFs) in response to glutamine deficiency." (PMID 37891897, 2023). "The pharmacological mechanism was also revealed: in the perspective of proteomics, JorA mainly modulates the expression level of EGFR, Bid, and Bcl, which belong to the "pathways in cancer" signaling pathway." (PMID 37587470, 2023). "Targeted agents selectively target the molecular pathways of cancer cells, such as the epidermal growth factor receptor (EGFR) pathway that regulates functions related to cell proliferation, growth, and apoptosis." (PMID 38067353, 2023). "For SM, we identified 118 co-targeted genes of active components and AIC, which were significantly enriched in pathways of cancer pathways, EGFR tyrosine kinase inhibitor resistance and AGE-RAGE signaling pathway in diabetic complications." (PMID 37168657, 2023). "EGFR is a highly expressed antigen in many cancers, including HNSCC, and its levels of expression have been shown to correlate with disease severity; therefore, cancer therapeutics targeting EGFR, such as cetuximab, have been developed and proved efficacious." (PMID 37958293, 2023). "It was hypothesized that EGFR is unimportant for those types of cancers that are innately resistant to EGFR kinase inhibitors, but this idea was invalidated by new evidence showing that even in innately resistant cancer types, the downregulation of EGFR proteins causes severe cell death." (PMID 37446288, 2023). "In this context, we have previously reported the development, characterization, and specificity of a dual function antibody conjugate (DFAC) for multi-modal imaging and photoimmunotherapy (PIT) of EGFR over-expressing cancer cells." (PMID 36778405, 2023). "Epidermal growth factor receptor (EGFR) is a proto-oncogene; high expression of EGFR was found in many human cancers and is associated with a poor prognosis." (PMID 37588336, 2023). "EGFR plays roles in malignant transformation and cancer metastasis, and its dysregulated activation has been regarded as multifaceted hallmarks of cancer cells." (PMID 36841821, 2023). "The EGFR signaling cascade is a key regulator of cell proliferation, differentiation, division, survival, and cancer development." (PMID 36982500, 2023). "Genistein, a natural isoflavone from soybeans, inhibits cancer cell growth by targeting protein tyrosine kinases and growth receptors like EGFR and ER." (PMID 38249515, 2023). "The epidermal growth factor receptor (EGFR) is a well-studied receptor tyrosine kinase that plays a vital role in regulating organ development and cancer progression, especially in NSCLC." (PMID 36674964, 2023).